CXCL8 (C-X-C motif chemokine ligand 8)
Diseases named in the same sentence as CXCL8 in open-access papers (continued):
Sharing a sentence is not in itself a finding about the gene and the disease.
tumor (continued). "CXCL8 and CXCL10 promote ECM degradation by inducing overexpression of MMP-2 and MMP-9, thereby creating a gateway for tumor cell invasion." (PMID 41445742, 2025). "The results showed that CXCL8, through binding to CXCR1/2, activates the PI3K/AKT and MAPK signaling pathways, enhancing the migration and invasion capabilities of tumor cells." (PMID 40573881, 2025). "In contrast to what was observed for the ligand CXCL8, a reduction of the levels of its receptor CXCR2, was observed in both normal and tumor thyroid cells following treatment with AZD5069 [1 μM]." (PMID 38900374, 2025). "For example, CAR-T cells expressing CXCR2 or CCR5 have demonstrated improved migration toward tumours that produce CXCL1, CXCL8, or CCL5." (PMID 40624498, 2025). "The role of IL-8/CXCL8 in the tumor microenvironment is less understood, although it has been suggested that it promotes tumor cell proliferation and migration." (PMID 40061210, 2025). "CXCL8, a pro-inflammatory chemokine, binds CXCR1/CXCR2 receptors to drive tumor progression via TME interactions." (PMID 40596054, 2025). "Recent studies have revealed several new crosstalk mechanisms between CXCL8 and components of the tumor microenvironment (TME), which can suppress anti-tumor immunity, promote tumor progression, and even create positive feedback loops." (PMID 40573881, 2025). "Evidence also found that in tumor cells with HDAC3 knockout, the expression of CXCL8 was significantly upregulated." (PMID 40573881, 2025). "TAMs, a crucial element of the TNBC IME, have the ability to secrete numerous pro-tumorigenic factors, including CXCL8 and CXCL1, which influence tumor cell behavior and foster the development of tumor spheroids in TNBC cells." (PMID 40149989, 2025). "Post androgen deprivation therapy in prostate cancer shows significant upregulation of certain chemokines such as CXCL8 and CXCL15, which facilitates the recruitment of PMN-MDSC to the tumour microenvironment." (PMID 40852716, 2025). "Initial candidates for overexpression have been the chemokine receptors CCR2 and CXCR2 (receptors for CCL2 and CXCL8/IL-8, respectively) for CAR and transgenic TCR T cells, as well as TILs, which revealed increased tumor infiltration in several models." (PMID 41181132, 2025). "A number of ligands, including CXCL1, CXCL2, CXCL5, and CXCL8, converge on CXCR2, thereby coordinating neutrophil recruitment, angiogenesis, epithelial–mesenchymal transition, and tumor proliferation." (PMID 40943634, 2025). "Neutrophils also release chemokines, including CXCL3, CXCL8, and CXCL10, which recruit additional immune cells to the tumor site." (PMID 40227814, 2025). "Studies have reported that the mRNA expression of CXCL8, a ligand for CXCR2, is markedly higher in tumor tissues, which is expected to be a candidate biomarker for ESCC." (PMID 40722739, 2025). "CXCL8 was also found to be significantly upregulated in HCC, promoting tumor progression and metastasis through activation of the AKT/mammalian rapamycin target protein (mTOR)/STAT3 pathway." (PMID 40145607, 2025). "Neutrophils can be recruited by chemoattractants, such as CXCL8/IL-8, CXCL12/SDF-1, VEGF, S100A8, and S100A9, secreted both from the primary tumor and from stroma cells in the PMN." (PMID 40370456, 2025). "In vivo and in vitro CXCL8 and CLU expression levels in tumor cells were determined using qPCR, immunohistochemistry and ELISA." (PMID 39905539, 2025). "IL‐8, also known as chemokine CXCL8, is a chemokine containing the ELR (glutamate leucine arginine) sequence that can promote tumor cell stemness and metastasis." (PMID 40859900, 2025). "In summary, our results showed no indication for Fusobacterium-mediated M2 polarization of macrophages in the CRC tumor samples but, in contrast, a pro-inflammatory TME driven by inflammatory cytokines such as CXCL8, IL-6, and TNF-α." (PMID 40895532, 2025).
tumor (continued). "Upon being recruited to inflammatory tumor tissues in response to chemokines like CCL2, CCL5, CXCL8, and CXCL12, MDSCs rapidly produce immunosuppressive mediators, including ARG1, NO, TGF-β, and IL-10, which further impair anti-tumor immunity." (PMID 40563367, 2025). "The study further revealed that targeting the CXCL8 pathway and PD-1 inhibition synergistically increased the tumor immune response and TNBC tumor suppression." (PMID 40141437, 2025). "Numerous studies revealed that chemokines such as CXCL1, CXCL2, IL-8 (CXCL8), CXCL5, CXCL12, CCL2, and MIP-1α (CCL3) promote the infiltration of neutrophil to the tumoural microenvironment." (PMID 40852716, 2025). "CAAs are better equipped to support tumor invasion and metastasis by releasing CCL2, CCL5, CXCL8, IL-6, leptin, adiponectin, and VEGF." (PMID 40076892, 2025). "CCL4, CXCL8, and MIF have been shown to induce angiogenesis and immune escape of tumor cells and promote the progression of many human cancers 10-13." (PMID 40092701, 2025). "The directional movement of PMN-MDSCs is modulated by the release of C-X-C motif chemokines from tumor cells, including CXCL1, CXCL5, CXCL6, CXCL8, and CXCL12." (PMID 40722739, 2025). "Interleukin 8 (IL-8 or CXCL8), a chemokine secreted by myeloid, endothelial, epithelial, and tumor cells, attracts neutrophils to areas of inflammation." (PMID 38493133, 2024). "METs-triggered CXCL8 plays a role in promoting crosstalk with tumours, enhancing EMT alongside other soluble cytokines and facilitating tumour cell adherence to the endothelium." (PMID 39025845, 2024). "LAPTM4B-produced CXCL8 attracts MDSCs to TME and triggers neutrophil MDSCs to extrude NETs, facilitating tumor cell nesting." (PMID 38388484, 2024). "Tumor size was positively correlated with levels of CXCL1 (r = 0.17, P = 0.048), CXCL8 (r = 0.18, P = 0.037), and IL6 (r = 0.27, P = 0.009)." (PMID 38965454, 2024). "Human CXCL8 translation was specifically controlled by METTL1-mediated m7G tRNA alteration, allowing MDSC to accumulate in the tumor immunological environment to accelerate ICC progression in vivo." (PMID 38641828, 2024). "The blockade of CXCL8 or NFATc1 largely attenuated neutrophil infiltration, NET formation, and tumor promotion induced by SKAP1." (PMID 39269257, 2024). "Our study emphasized the role of IL6high CAF on tumor cells for elevating level of various cytokine genes including IL6, IL32, IL33, CXCL1, CXCL3 and CXCL8, and oncogenic pathways, such as the Wnt and VEGF signaling pathways." (PMID 38892065, 2024). "Mechanistically, MLKL-driven necroptosis recruits macrophages, enhances the tumor CD47 ‘don’t eat me’ signal, and induces macrophage extracellular traps (MET) formation for CXCL8 activation." (PMID 39025845, 2024). "IL-17A can selectively elevate the expression of chemokines with angiogenic properties by epithelial cells as well as tumor cells, such as CXCL1, CXCL5, CXCL6, and CXCL8." (PMID 38515019, 2024). "As a tumor escape mechanism, tumor cells release high levels of transforming growth factor β (TGF-β) and CXCL8 to enhance growth and invasion via inducing angiogenesis." (PMID 38515019, 2024). "For example, CXCL8, a member of the CXC cytokine family, is one of the most significantly upregulated chemokines in CRC, contributing to tumor growth, invasion, and metastasis." (PMID 38243058, 2024). "M-MDSCs are rapidly recruited to the inflammatory tumor tissues upon exposure to chemokines such as CCL2, CCL5, CXCL8, and CXCL12 and produce multiple immunosuppressive cytokines such as ARG1, nitric oxide (NO), TGF-β, and IL-10." (PMID 38520006, 2024). "ELR+ includes CXCL1, CXCL2, CXCL3, CXCL5, CXCL6, CXCL7, and CXCL8, which binds to the receptor CXCR2, that are overexpressed in microvascular ECs and tumor vessels, and enhances angiogenesis." (PMID 38213742, 2024).
tumor (continued). "On the one hand, in the TME, MCs can release angiogenic molecules such as VEGF-A, CXCL-8, FGF-2, VEGF-C, MMP-2, and MMP-9, thus promoting tumor vascularization and invasiveness." (PMID 39126091, 2024). "Treatment with IFN-γ inhibited the CXCL8 released, diminishing TAM trafficking and enhancing ICI anti-tumor effects." (PMID 38339310, 2024). "High variability genes in monocyte_C02 cells, including CXCL8, TNFAIP6, CXCL3, and SPP1, indicate a potential role in tumor promotion." (PMID 38711918, 2024). "This leads to the re-expression of CXCL8/IL-8, partially restoring TAM recruitment and tumor progression." (PMID 38720342, 2024). "A significant increase in UCK2, HMMR, and MAGEA6 expression and a significant decrease in CXCL8, EPO, PPARGC1A, FTCD, and CFHR3 expression was observed in tumor tissues." (PMID 38694506, 2024). "The typical molecular inflammatory signature in the tumor microenvironment includes both proinflammatory cytokine (IL-1, TNF-α, IL-6, and IL-8) and chemokines (CCL20, CXCL13, and CXCL8)." (PMID 38256080, 2024). "For example, both IL-6 and CXCL8 are reported to be elevated in KRAS-driven STK11-null LUADs and proposed to promote tumor immune evasion." (PMID 37968341, 2024). "IL-17A produced by neutrophils exacerbates tumor growth by inducing CXC chemokines (CXCL1, CXCL2, CXCL3, CXCL5, CXCL8, and CXCL11) in gastric cancer cells to recruit neutrophils to the invasive edge." (PMID 39906741, 2024). "Bidirectional crosstalk between tumor cells and CAFs enhances the ability of fibroblasts to secrete various pro-tumor chemokines, including CXCL12/CXCR4 axis, CCL2, CCL5, CCL7, CXCL8, and CXCL14." (PMID 39092186, 2024). "Studies suggest CXCL8 can accelerate tumor cell proliferation, epithelial–mesenchymal transition (EMT), angiogenesis, and impede anti-tumor immunity." (PMID 38711918, 2024). "Combination therapy with adagrasib and pembrolizumab has demonstrated increased CD8 infiltration and anti-tumor response by downregulating CXCL1, CXCL8, VEGF, and CD73, reshaping the TME and facilitating TIL infiltration." (PMID 38785789, 2024). "The immune genes CXCL1, CXCL2, IL1B, IL6, CXCL8, PTGS2, and SPP1 demonstrated elevated expression levels in tumor tissue (TU) relative to all other tissues, thus validating the results obtained from the NanoString analysis (Supplementary 1)." (PMID 38979413, 2024). "Dysregulation of the interaction center will form a strong tumor promoting microenvironment, which, in combination with the activation of chemokines such as CXCL1 and CXCL8, will jointly drive cancer cell invasion and promote disease progression." (PMID 37968342, 2024). "Our study identified four critical DEGs (CXCL8, PSMC2, APP, and SLC20A1) that demonstrated high performance in identifying CRC in diverse populations and ethnicities, covering a range of tumor stages and histologic grades." (PMID 38243058, 2024). "These suggested CXCL8 is a critical mediator between HCC cells and pro-tumor neutrophils/NETs in cirrhotic-ECM enriched TME." (PMID 38388466, 2024). "It is noteworthy that ATR-101 therapy also partially reversed the effects of tumor-cell conditioned medium on the expression of HIF1A, VEGFA, and CXCL8 in TAM-like cells, but M0 macrophages were unaffected." (PMID 37426676, 2023). "CXCL8, a proinflammatory chemokine that is also known as interleukin 8 (IL8), showed a positive correlation with tumour necrosis in both Cohorts 2A and 2B (beta = 0.206 and 0.209, P = 0.009 and 0.035, respectively)." (PMID 37031328, 2023). "CAF-derived chemokines such as IL-8 or CXCL8 recruit immunosuppressive cells to the TME, consequently enabling effective tumor progression, angiogenesis, and EMT." (PMID 36793444, 2023). "Neutrophils can be recruited into the TME by various cytokines, such as IL8, MIF, and CXCL8, which in turn leads to aggressive tumor growth and therapeutic resistance in GBM." (PMID 36923402, 2023).
tumor (continued). "IL-6 and CXCL8, important autocrines in TNBC, were known to activate neutrophils and NK cells migration to the tumor." (PMID 37334114, 2023). "Mast cells release VEGF-A, VEGF-C, VEGF-F, CXCL-8, MMP-9, and other factors, which promote tumor angiogenesis." (PMID 37161430, 2023). "Interleukin-8 (IL-8), part of the CXC chemokine family known as CXCL8, regulates pathological angiogenesis and tumor growth." (PMID 37892657, 2023). "MSCs can also secrete chemoattractants, including CXCL1, CCL5, CXCL5, CXCL8 and CXCL7, which promote tumor cell migration to metastatic lesions." (PMID 36926687, 2023). "Tumor cells secrete CXCL1 and CXCL8 to recruit neutrophils, activate the ERK and JNK pathways in neutrophils, and express VEGF-A and MMP-9, leading to LN metastasis." (PMID 38129401, 2023). "The expression of TF-protein YY1 (a regulator of CXCL8, ADH1C, CEMIP, ZG16, and CLCA4) contributes to tumor growth differs in different cancers." (PMID 36991484, 2023). "Positive predictive values (PPV) for CXCL8 and CXCR2 were higher than for the classical tumor marker CA19-9." (PMID 37240178, 2023). "In HCC, monocyte-derived CXCL2 and CXCL8 can recruit peripheral neutrophils to TME and sustain their survival, and tumor cells then educate the peripheral blood neutrophils to develop into CCL2 + or CCL17 + TANs via PI3K/Akt and p38/MAPK signaling pathways." (PMID 36773210, 2023). "Biochemical signals include the secretion of growth factors (VEGF, EGF, FGF, PDGF), pro-inflammatory cytokines (IL-6, IL-8, TNF) and pro-metastatic chemokines (CXCL8, CCL2, CCL5), among others, that induce tumour proliferation and motility." (PMID 37868949, 2023). "The diagnostic sensitivity of CXCL8 was higher than the well-known tumor marker, CEA, and higher than the specific receptor for CXCL8 (CXCR2)." (PMID 37240178, 2023). "Thus, the immune chemokines CXCL8, CXCL3, and CCL20, which are positively associated with SLC7A11, have SLC7A11-like functions in the development of tumours and provide evidence of association at the tumour immune microenvironment level for poor prognosis in ACC patients with SLC7A11high." (PMID 37919768, 2023). "Low passage tumor alone secreted high concentrations of CCL2/MCP1, CXCL8/IL-8, CXCL1/GRO, IL-6, CXCL10/IP10, G-CSF, TGFβ1, MMP1, CCL3/MIPα, GM-CSF and EGF." (PMID 37063842, 2023). "In HCC patients, tumor cells secrete CXC chemokines, especially CXCL8, to attract neutrophil accumulation in the peritumor stroma." (PMID 37275909, 2023). "CXCR1 and CXCR2 have comparable affinity to CXCL6 and CXCL8 (IL-8), and CXCR2 mediates tumor angiogenesis." (PMID 37626511, 2023). "Trabectedin exerts its activity on both tumor cells and the tumor microenvironment by reducing the production of inflammatory mediators (e.g., CCL2 or CXCL8)." (PMID 36857355, 2023). "CRC cells are able to regulate CXCL8 in an autocrine manner and increase the expression of CXCR1 and CXCR2, which contributes to tumor development through the invasion, dissemination and metastasis of cancer cells." (PMID 37509572, 2023). "In their study, worse tumor features and poor overall survival in patients with CRC were influenced by CXCL1, CXCL2, CXCL8 and CXCL13, which contributed to CRC treatments." (PMID 37393391, 2023). "CXCL8, the key ligand of CXCR1/2, is overexpressed in various solid tumors and has been shown to promote tumor development." (PMID 37540227, 2023). "For instance, circulating hypoxia activated hypoxia-inducible factor 1(HIF-1) and NF-κB in tumor cells, which resulted in increased production of VEGF-A, CCL2/MCP-1, CXCL1, CXCL8/IL-8 and prostaglandin E2(PGE2)." (PMID 36173487, 2023). "Exosomes and tumor mRNA from primary OC and LN metastatic patients were analyzed for their quantitative gene expression patterns of MMP9, CXCL8, and FN1." (PMID 37640804, 2023). "In summary, tumor cell-derived chemokines and cytokines, such as CXCL1/CXCL8 and SRF, recruit MDSCs, TAMs, Treg and Tex, and interact with target genes, like MIF and IFNG." (PMID 37940972, 2023).
tumor (continued). "Macrophages are recruited in tumor sites by various chemokines such as CSF-1, CCL2, 5, CXCL8, and 12, which are secreted from TME." (PMID 38017494, 2023). "The qRT-PCR results demonstrated that four cellular senescence-related genes (CENPA, CXCL8, EZH2, and G6PD) and two chemokine-related genes (CCL26 and CXCL5) were overexpressed in tumor tissues from HCC patients compared with paraneoplastic tissues." (PMID 36670201, 2023). "IFNG, produced by Tex, also exhibited increased interaction with CXCL8/1 in the EMTPs of both stages, which is critical for CRC tumor invasion and deserves further analysis." (PMID 37940972, 2023). "CXCL8 and vascular endothelial growth factor (VEGF)-A secretion from poorly DTC is induced by thyroid-stimulating hormone (TSH) signaling, which regulates tumor angiogenesis, macrophage infiltration, and enhanced tumor growth." (PMID 38250858, 2023). "The expression of CXCL8 was increased in CK7- and phospho-Smad3-positive acinar-type tumor tissue compared with solid-type tumor tissue in the A549 xenograft model, as well as in human LADC tissue and mutant KRAS-driven mouse lung cancer tissue." (PMID 37174001, 2023). "In line with this study, it was reported that activated inflammatory DCs induced γδT17 cells to secrete CXCL8, TNF-α and CSF2 with a concomitant accumulation of PMN-MDSC with high arginase-1 and ROS production in the tumor." (PMID 37566060, 2023). "CXCL8 mainly functions through its interactions with CXCR1 and CXCR2, and CXCL8/CXCR1 contributes to the proliferation of tumor cells." (PMID 36647133, 2023). "The components in the TME can directly secrete metabolites (such as IL-6, FGF-2, PDGF, MMPs, CXC12, VEGF, FGF, IL8/CXCL8, and PDGF-C) that induce tumor metastasis and tumor cell proliferation." (PMID 35571530, 2022). "Except for CXCL8 and CCL20, all hub genes have significantly lower expression in advanced tumor stages." (PMID 36003333, 2022). "In vitro treatment with trabectedin decreased the production of CCL2, CXCL8, IL-6, VEGF and PTX3 by myxoid liposarcoma (MLS) primary tumor cultures and/or cell lines, and freshly isolated ovarian cancer cells from ascites." (PMID 35299737, 2022). "Both OSCC tumour and serum expression of CXCL8/IL8 (C-X-C motif chemokine ligand 8/interleukin-8) were previously shown to be correlated with poor clinical outcome." (PMID 35326543, 2022). "Chemokines (CXCL12, CXCL8, CXCL5) and chemokine receptors (CXCR1/2, CCR4, CCR8) are well-known to deeply participate in the tumor development and progression in various cancers, including LUAD." (PMID 36419650, 2022). "A total of six upregulated genes (FN1, APOA1, CXCL8, MMP1, MMP3, and THBS1) in tumor tissue were identified by the differential analysis of 10 hub genes." (PMID 35719376, 2022). "The CXCL8 gene showed oncogenic, while IGF1 exhibited tumor suppressor features in tumor fibroblasts." (PMID 36357663, 2022). "MMP9_macro expressed genes related to inflammatory chemokines (CXCL2, CXCL3, CXCL8) and genes like MMPs (MMP19, MMP9), which play an important role in tumor tissue remodeling." (PMID 35935940, 2022). "Tumour-infiltrating leukocytes, endothelial cells, and fibroblasts express the CXC chemokine ligands CXCL1, CXCL2, CXCL5, CXCL6, and CXCL8 (also known as IL-8)." (PMID 35860278, 2022). "Once they reach the tumor site, TANs secrete a vast set of factors potentially involved in the biology of CCA (such as MMP-8, MMP-9, CXCL1, CXCL2, CXCL6, CXCL8, CCL7, and VEGF)." (PMID 39301518, 2022). "In in vivo experiments, using a xenograft mouse model of human MLS, a marked reduction of human CCL2, CXCL8 and PTX3 after trabectedin administration was observed, demonstrating that this effect on tumor cells occurs also in vivo." (PMID 35299737, 2022). "In stromally dense tumours (>50% TSP), there was a significant elevation in tumour CXCL8 expression (p = 0.010) and a trend towards higher stromal CXCL8 (p = 0.067) when assessed via non‐parametric Kruskal–Wallis H tests." (PMID 35879507, 2022).